IRF1 (interferon regulatory factor 1)
Diseases named in the same sentence as IRF1 in open-access papers (continued):
Sharing a sentence is not in itself a finding about the gene and the disease.
cancer (continued). "Immunostaining of candidate proteins MAX, TCF7L2, YY1, IRF1, STAT6, SP1, and E2F1 (selected based on qPCR results and/or associations to cancer in general) was performed in additional FTC specimens as outlined in the “Materials and Methods” section." (PMID 33063251, 2020). "Further activated transcription regulators, such as β-catenin, Foxm1, Irf1, Myc, Mitf, Tbx2 with a somewhat lower z-score did also point to cell cycle regulation, DNA damage and cancer development." (PMID 32419051, 2020). "The IFN-γ-mediated PD-L1 upregulation occurs mainly through JAK/STAT/IRF1 signaling pathway activation in several types of cancers, including NSCLC, resulting in binding of IRF1 to the CD274 promoter." (PMID 33114576, 2020). "As even low IRF1 expression affects cancer cell growth we used this system as it promotes a much more robust silencing of IRF1 expression prior to the addition of Dox." (PMID 30854564, 2019). "Our previous studies demonstrated that IFN-γ is one of the strongest inducers of IRF-1 expression in cancer cells." (PMID 31186404, 2019). "In the context of cancer, IRF1 is required for Th1 polarization in NK cells, mature CD8+ T cells, and M1 macrophages." (PMID 31319484, 2019). "Collectively, our data supports an essential contribution of GSK3β-Fbxw7α to the tightly regulated turnover of IRF1 protein during the transcriptional cycle and, thus its anti-cancer activities." (PMID 30854564, 2019). "More importantly, IRF-1 is increasingly thought to play an important role in the development of malignant tumours." (PMID 31186404, 2019). "IRF-1 is a nuclear transcription regulator that has an important role in cancer proliferation, apoptosis and the DNA damage response." (PMID 31186404, 2019). "The various mechanisms involved in IRF-1 inactivation in human cancers involve processes at DNA, RNA, and protein levels." (PMID 29599126, 2018). "The data summarized in this review suggest that more research should be conducted to explore the potential utility of the IRF-1 as a therapeutic target in cancer." (PMID 29599126, 2018). "That IRF-1 is a potential target for new therapies has been highlighted by correlations between its inactivation and several types of human cancers." (PMID 29599126, 2018). "In this study we showed activation of the IRF1/IFN-κ/P-STAT1 signaling cascade in the epidermal compartment of the inflammatory lesions manifesting in the skin of cancer patients treated with cetuximab." (PMID 30200670, 2018). "Using knockout and a chemical inhibitor, our data show that JAK2 was necessary for IFNγ-induced IRF1 and cancer cell surface expression of HLA-ABC MHC class I molecules." (PMID 28977839, 2017). "Examination of TCGA data of 881 cancer cell lines in the cancer cell line encyclopedia (CCLE) cohorts again showed that the IFNγ-IRF1 pathway genetic defects in these cancer cells occurred most often through JAK2 deletion." (PMID 28977839, 2017). "Oncogenic activation of Ras/MEK downregulates the expression of interferon regulatory factor 1 (IRF1), which is a prerequisite for oncolytic viruses to replicate in cancer cells." (PMID 27508303, 2016). "The long non-coding RNA (lncRNA) HOX transcript antisense RNA (HOTAIR) plays a crucial role in cancer progression, which is regulated by the interferon regulatory factor-1 (IRF1) and up-streaming Akt activation." (PMID 27388461, 2016). "Conversely, IRF1 overexpression in cancer cell lines suppresses cancer cell cycle transition, apoptosis and caspase activation." (PMID 25980475, 2015). "Ras/MEK signaling has been shown to suppress IFN regulated genes in human cancer cells probably by suppressing IRF1." (PMID 26572553, 2015). "A major difference is that interferon-γ and IFN-γ-induced interferon regulatory factor-1 in the IL-2-STAT4 pathway are overexpressed in EBV-positive cancers versus uninfected cancers." (PMID 25613731, 2015).
cancer (continued). "IFN-γ is an essential mediator of the immune response to viruses and cancer and is one of the strongest inducers of IRF-1 expression in cancer cells." (PMID 24650050, 2014). "Collectively, these studies indicate that genetic alterations of IRF-1 are important for the development of specific types of human cancer." (PMID 23420765, 2013). "IFN-α and IFN-γ enhance TRAIL expression via a STAT1– and IRF-1–dependent mechanism in cancer cells." (PMID 24155891, 2013). "This preliminary data suggests that PHY906 works in the context of chemotherapy by enhancing inflammation through IRF-5 while blocking the anti-apoptotic effects likely activated by cancer cells through the suppression of IRF-1 expression." (PMID 21569348, 2011). "Expression of Interferon regulatory factor-1 (IRF-1) has been demonstrated in a variety of cancers previously." (PMID 20606993, 2010). "IRF1, a classical downstream target of IFNγ, functions as a transcription factor critical in mediating IFNγ-induced anti-proliferation, apoptosis, invasion inhibition, and antitumor immunity in cancer." (PMID 41218553, 2025). "In CXCL12 synovial fibroblast cells from RA patients, SDC2 was found to have a role in extracellular matrix remodeling, suggesting that IRF1 may have a similar role in cancer." (PMID 40862725, 2025). "The critical function of IRF1 in the immune systems of various cancers has been explored, the clinical application and biological function of IRF1 in NSCLC patients who receiving chemoimmunotherapy remains unknown." (PMID 38915471, 2024). "CCK-8 and colony formation experiments indicated that CsnB strongly suppressed ESCC cell proliferation, while this inhibitory effect on cancer cells could be reversed by overexpressing IRF1 in Kyse520 and TE-1 cells." (PMID 38789431, 2024). "Similarly, systemic treatment with a type I IFN inducer, poly I:C, reversed resistance of IRF2 null cells to CPI in vivo and this salutatory effect was also dependent on IRF1 in the cancer cells." (PMID 39281881, 2024). "And IRF1 is a master transcription factor in the Interferon-γ pathway, playing important roles in apoptosis, inflammation, cell growth and polarization, oncogenesis, and cancers are well documented." (PMID 39605886, 2024). "Clinically, p-NF-κB, p-STAT1, and IRF1 expressions were examined in benign and cancer tissue." (PMID 38540186, 2024). "To investigate whether the identified PARP7/FRA1/IRF1/IRF3 axis is observed in other cancer cell lines, we compared FRA1 and PARP7 expression levels across 1,078 cell lines from various origins using the DepMap project dataset." (PMID 38011562, 2023). "These indicated that adaptive immunity, including cytotoxic CD8 T-cells and helper CD4 T-cells with Th1 signature (IFNG, IL12, IRF1), might arise before the carcinoma stage." (PMID 36672367, 2023). "However, in many cancers, the functions of IRF1 in cell death and in cell cycle regulation are impaired." (PMID 35406498, 2022). "Interestingly, the contribution of IRF1 to CD274 expression relative to that of other significant TFs differed amongst cancer types (15% [SD: 1.4] in BRCA, 26% [SD: 2.1] in LUAD, and 56% [SD: 3.9] in SKCM)." (PMID 35289334, 2022). "E7 also recruits HDAC1/2 to the tumor suppressor IRF-1, thus inhibiting IRF-1 transcriptional activation and the production of IFN-β, suggesting a possible mechanism underlying immune evasion, frequently observed in HPV+ cancers." (PMID 35408843, 2022). "However, the ability of BCA2 to interact with IRF1 seems to be lost in more aggressive cancer cell lines like the ER–." (PMID 34589482, 2021).
cancer (continued). "PD-L1 upregulation was found to be associated with increased expression of γH2AX (a DSB marker) and IRF-1 (a PD-L1 inducer) in clinical UC-associated dysplasia and colitic cancer tissues but not in SCRC tissues or the corresponding non-cancerous UC mucosa." (PMID 34158547, 2021). "UBE2D2 and NFKB2 may go through TLR4 to influence IRF1 to destroy the immune system and promote the occurrence and development of cancer." (PMID 34445498, 2021). "Therefore, it would be interesting to investigate the role of STAT1 and STAT2 as well as KPNA1 in radiation-increased KPNB1-mediated IRF1 expression in these cancers." (PMID 34069326, 2021). "Finally, we investigated the role of IRF1, a central transcription factor involved in IFN responses that has been implicated in necroptosis in a variety of cancer cells." (PMID 34462421, 2021). "Although this activity of BCA2 is independent of its catalytic activity, we investigated whether BCA2 loses control over IRF1 in the cancer environment." (PMID 34589482, 2021). "Overall, the mechanistic understanding of MAPK/IRF1-mediated intratumoral reprogramming may ultimately prolong the efficacy of targeted drugs in genetically defined cancer patients." (PMID 34535668, 2021). "IRF-1 upregulation was associated with γH2AX upregulation in UC-associated dysplasia/colitic cancer but not in SCRC." (PMID 34158547, 2021). "IPA of the 37 plasma-derived sEV protein features with ROC AUCs ≥ 0.70 revealed NKX3-1 (p = 1.4 × 10−9) as a top causal network, Cancer, Cell Death and Survival as a top disease function (p = 1.57 × 10−8) and AHR, VEGF, EGF, IRF1 and STAT3 as predicted significant upstream regulators." (PMID 32370304, 2020). "Interestingly, negative regulators of enhancer-associated genes including the TFs CEBPA, IRF8, IRF1 and ETV6, can suppress cancer cell growths." (PMID 31665430, 2020). "IRF1 has been found to have a central role in the immunologically active cancer phenotype." (PMID 32346613, 2020). "Moreover, we unveiled a novel mechanism of FOXM1c in regulating cancer invasion and migration, that is, FOXM1c transcriptionally regulated IRF1 by directly binding to its promoter region, and IRF1 further modulated MMP2/9 expression." (PMID 30485581, 2019). "In addition, interaction between GAGE proteins and IRF-1 has been reported in cancer cells, possibly explaining GAGE-induced cell survival and resistance to IFN-γ treatment." (PMID 29599126, 2018). "Cancer cells could escape the effects of IFN-γ by downregulating or mutating molecules including IFNGR1/2, JAK2, and IRF1." (PMID 29299180, 2017). "It is hypothesized that the IFNγ-inducibility of IRF1 predicts better responsiveness to anti-cancer therapy." (PMID 27966453, 2017). "Furthermore, we demonstrated that MEK inhibition restored IRF1 expression in human cancer cells and that the level of IRF1 expression defines the sensitivity of cancer cells to certain oncolytic viruses." (PMID 27508303, 2016). "Moreover, restoration of IRF1 expression is essential to induce apoptosis of cancer cells treated with a MEK inhibitor." (PMID 27508303, 2016). "IRF2 is a functional antagonist of IRF1 and may act as an oncogene, promoting the formation and progression of cancer." (PMID 27806724, 2016). "A practical consequence of our study is the suggestion that strategies to induce RelA or IRF1 activity may also be useful in patients with Rb-competent cancers." (PMID 26460486, 2015). "The down-regulation of IRF1 expression by miRNAs has been reported in a variety of human cancers." (PMID 25980475, 2015). "IRF1 also acts as a negative growth regulator, and loss of IRF1 function has been associated with transformation in several cancers, including pre-leukaemic myelo-dysplastic syndromes." (PMID 24954358, 2014). "Therefore, our observation of upregulated IRF1 in NSCLC samples requires further attention to explore the precise role of this TF in various cancers." (PMID 24564251, 2013).
cancer (continued). "In addition, numerous clinical studies have indicated that IRF-1 gene deletion or rearrangement correlates with development of specific forms of human cancer." (PMID 23420765, 2013). "Accumulating evidence indicates that deletion or inactivation of the IRF-1 gene may be a critical step in the development of specific types of human cancer." (PMID 23420765, 2013). "Thus, it is possible that activation of the IFN-γ/STAT-1/IRF-1 pathways serves to counteract the constitutive activation of STAT-3 in some cancer cell lines in the context of metastatic melanoma." (PMID 21875439, 2011). "The upregulation of interferon-related genes (Stat1, Irf1) suggests activation of antitumor immune responses, while downregulation of metabolic enzymes like Enox1 may indicate metabolic reprogramming of cancer cells." (PMID 40969227, 2025). "Similarly, it would be on interest to determine whether a cancer’s levels of IRF1 and IRF2 might be biomarkers for tumors that might benefit IFN treatment to improve the efficacy of CPI." (PMID 39281881, 2024). "Thus, while the contributions of SPOP to cancer establishment or progression are likely through deregulation of a manifold of its substrates, our work suggests that IRF1 may be one of them." (PMID 37622993, 2023). "Moreover, PD-L1 upregulation in UC-associated dysplasia/colitic cancer was significantly associated with γH2AX (P = 0.024) and IRF-1 (P = 0.002) upregulation but not with CD8 expression (P = 0.103)." (PMID 34158547, 2021). "Indeed cancer cell lines with detective Fbxw7α are largely resistant to the anti-proliferative activities of IRF1 suggesting that Fbxw7α is an important co-activator of IRF1 function." (PMID 30854564, 2019). "Moreover, IRF1 has associated with inhibition of EMT, migration and invasion of some cancer cells." (PMID 31113461, 2019). "However, survivin may also be regulated in human cancer cells by other IRF-1 signaling pathways or directly by IRF-1 itself." (PMID 29599126, 2018). "Interestingly, IRF1 and a variant of heterogeneous nuclear ribonucleoprotein L (Lv1) coordinately regulate CEACAM1 transcription, alternative splicing, and translation, and may significantly contribute to CEACAM1 silencing in cancer." (PMID 40002189, 2025). "In the present study, we found that TNF, IFN, IRF1 and IRF5, IL-6, IL-1β, and CCL3 were upregulated in EBV-positive SCC25 cancer cells compared to EBV-negative SCC25 cancer cells." (PMID 39941858, 2025). "Despite some differences, our data validated the YTHDF‐mediated regulation of IRF1 and IFN‐γ signaling in human cancer cells, affirming its relevance across species." (PMID 39587835, 2025). "The main mechanism is that after treatment with SeNPs, elevated ROS accumulation in cancer cells activates TNF and interferon regulatory factor 1 (IRF1), which ultimately leads to an increase in RIP1 protein expression inducing necroptosis." (PMID 38652105, 2024). "Of these genes, TAP2, B2M, IRF1, TAP1, HLA-A, HLA-B and HLA-C were formally and independently classed as CRC drivers, with strongest signals in MSI cancers, but also discovered in MSS cancers (for example, HLA-A and B2M)." (PMID 39112709, 2024). "Upon stimulation with EGF, EGFR activity is known to induce IRF1 gene cascades, largely through STAT1 phosphorylation/activation, in other cancer cell lines." (PMID 38339304, 2024). "For instance, IRF1 activates PANoptosis to prevent AOM/DSS-induced colorectal tumorigenesis, indicating a promising future for PANoptosis-related cancer research." (PMID 37298343, 2023). "Cluster 0 expressed many interferon-induced genes, such as ISG15, IRF1, ISG20, and more, which play a major role in the development and metastatic progression of cancers." (PMID 37158921, 2023).
cancer (continued). "Further analyzing transcriptomic data exhibited significantly positive Pearson correlation coefficients for most cancer entities between CXCR4 and the T cell co-receptors CD4 and CD8A, as well as IRF1 and CTLA4." (PMID 36672341, 2023). "The expression of IRF1 in NSCLC tissue was generally lower than that in normal lung tissue, which is cancer-suppressive by regulating KPNA2." (PMID 36245844, 2022). "And it has been previously reported that IRF1 and E2F1 can regulate the proliferation and metastasis of various cancer cells by affecting their downstream genes 33-37." (PMID 35154468, 2022). "Some TFs with cancer-related biological functions also showed high Jaccard scores with G4-II, such as E2F6, IRF1, and MYC." (PMID 36092921, 2022). "We therefore set out to quantify to what extent the PD-L1 mRNA level (CD274) in cancer patients can be predicted by activity of the relevant TFs MYC, HIF1A/2A, JUN, IRF1, STAT1/3, NFKB, and NRF2." (PMID 35289334, 2022). "In conclusion, we found IRF1 to be a general predictor for CD274 expression in all three studied cancer types, and STAT1, NFKB, HIF1A and BRD4 to be predictors for some of these cancer types." (PMID 35289334, 2022). "In conclusion, we found that ICD inducers activate IFNβ-IRF1 signaling, leading to the surface exposure of CRT in cancer cells." (PMID 32326356, 2020). "This review discusses the functions of IRF-1 and IRF-2 in human cancers, with a focus on the potential contribution of IRF-1 inactivation to human carcinogenesis and the future of IRF-1 as a therapeutic target." (PMID 29599126, 2018). "IRF1, directly participating in the regulation of PD-L1 expression, is essential in the constitutive and IFN-γ-induced expression of PD-L1 in various cancer cells." (PMID 30333036, 2018). "This review focusses on current knowledge of the roles of IRF-1 and IRF-2 in human cancer, with particular attention paid to the impact of IRF-1 inactivation." (PMID 29599126, 2018). "The promoter of the HOTAIR gene can be bound by interferon regulatory factor-1 (IRF1), which inhibits HOTAIR activity in cancer." (PMID 29469819, 2017). "In cancer, EGFR has been shown to have growth inhibitory effects as it induced the expression of IRF-1 via phosphorylation of STAT1 and STAT3." (PMID 26881744, 2016). "Further in vitro and in vivo studies are necessary to confirm this causal role and to uncover the mechanisms through which rs2522057 may regulate IRF1, RAD50, and SCL22A5 expression via CARINH, ultimately affecting cancer development." (PMID 41283334, 2025). "IRF-1 is located upstream of PD-L1 in the IFN-γ-driven JAK/STAT signaling pathway and has been shown to play a central role in regulating cancer cell responses to IFN-γ." (PMID 38633217, 2024). "Interestingly, AQP4_Astrocytes cluster derived from EPN highly expressed some anti-cancer genes, such as JUN, IRF1 and MSX1." (PMID 38383423, 2024). "When IRF1 is not working properly, it can lead to uncontrolled cell growth and division, which can eventually lead to cancer 146,148." (PMID 38169587, 2024). "With the assistance of interferon regulatory factor 1 (IRF1), IFN may trigger necroptosis in cancer cells when combined with Smac mimics." (PMID 38684668, 2024). "IRF1 and IRF2 were essential in regulating interferon activity, where the absence of IRF1 and the increase in IRF2 expression had been associated with aggressive traits in different types of cancer." (PMID 38999981, 2024). "The observation that IFNγ signaling and IRF1 expression are important biomarkers in ccRCC, addressing the importance of the SPOP-IRF1 axis in this cancer type may be of particular interest in future studies." (PMID 37622993, 2023). "Our results demonstrate that MUC1-C in a complex with STAT1 and IRF1 constitutively activates ISG15 transcription, in support of MUC1-C involvement in integrating chronic activation of the type I IFN pathway with induction of ISG15 expression in cancer cells." (PMID 35681561, 2022).